ABCB1 (ATP binding cassette subfamily B member 1)
Diseases named in the same sentence as ABCB1 in open-access papers (continued):
Sharing a sentence is not in itself a finding about the gene and the disease.
tumor (continued). "The drug efflux pump ABCB1 plays a key role in promoting chemoresistance by actively effluxing a broad range of chemotherapeutic agents from tumor cells." (PMID 32020017, 2020). "In the same group of patients the ABCB1 gene expression was also examined in 47 tumor tissues taken during the surgical procedure and compared to the expression level in the blood before the surgery and then to clinical-pathological features." (PMID 32277145, 2020). "Vice versa our data suggest the prevention of MARCKS inhibition by reversing hyperphosphorylation or genomic restoration after deletion as two promising approaches to overcome tumor cell resistance towards chemotherapeutic ABCB1 substrates." (PMID 32056006, 2020). "This study provides a promising therapeutic strategy to overcome ABCB1-mediated drug resistance of tumor cells." (PMID 32903706, 2020). "Results show that leptin signaling increases the expression of tumor progression and chemoresistance-related genes (ABCB1, WNT4, ADHFE1, TBC1D3, LL22NC03, RDH5, ITGB3) in TNBC cells." (PMID 32471192, 2020). "The higher anti-tumor activity of the combination of NZ and doxorubicin can be due to the additional down-regulation of ABCB1 that allowed an increased intratumor retention of doxorubicin and its cytotoxicity." (PMID 32155954, 2020). "More fascinatingly, in the xenograft tumor models, chemotherapeutical drugs also locally or distantly increase the transfer of ABCB1 molecules." (PMID 31830995, 2019). "It is notable that patient samples carrying ostensibly the same SLC25A40–ABCB1 fusion event differed in the overall level of ABCB1 expression, suggesting that fewer tumour cells carried the fusion event in ascites with lower ABCB1 expression." (PMID 30894541, 2019). "In total, 27 of 85 primary tumours (32%) were scored as positive for ABCB1 by standard immunohistochemical analysis, 15/53 (28%) from the CNS9204 trial cohort and 12/32 (37.5%) from the CNS9904 cohort." (PMID 31311995, 2019). "ABCG2/ABCB1 ratios in surgically resected tumor tissue (1.4 ± 0.2) were comparable to previously reported ABCG2/ABCB1 ratios in isolated human micro-vessels (1.3), which suggested that no overexpression of ABCB1 or ABCG2 occurred in the investigated tumors." (PMID 31832814, 2019). "ABCB1 positivity also correlated with reduced event free survival in patients with incompletely resected tumours who received chemotherapy across CNS9204 and CNS9904 (a radiotherapy-led SIOP 1999-04 trial cohort; p = 0.03)." (PMID 31311995, 2019). "Though we found expression of the multi-drug resistance gene P-glycoprotein 1/ABCB1 in normal PBMCs, its levels were equal or lower to those of tumour cell lines." (PMID 30792442, 2019). "In four subjects (p01, p02, p03 and p05), surgically resected tumor tissue was analyzed for ABCB1 and ABCG2 levels with QTAP." (PMID 31832814, 2019). "In order to assess the prognostic value of ABCB1 in all patients who received chemotherapy and explore the potential effect modification by tumour resection status, we combined the two trial datasets." (PMID 31311995, 2019). "Inhibition of ABCB1 efflux activity increases the accumulation of chemotherapeutic drugs in tumor cells with high expression of ABCB1, thereby enhancing the inhibitory effect of chemotherapeutic drugs on tumor cells." (PMID 30718500, 2019). "By contrast, for in vivo tissue, the main orientation of ABCB1 is apical‐in, with enrichment at central lumen‐facing cell membranes, both in normal colon crypts and in neoplastic tumour glands." (PMID 30306567, 2019). "ABCB1 was discovered as a protein overexpressed in certain drug-resistant tumor cells, and cells that overexpress this protein exhibit multi-drug resistance." (PMID 32038587, 2019). "This has raised interest searching for novel agents that selectively kill ABCB1/MDR1-expressing cells as alternative strategy to overcome MDR through tumor re-sensitization." (PMID 30515268, 2018).
tumor (continued). "ABCG2 and ABCB1 are expressed not only in tumor tissues but also in normal tissues including the liver." (PMID 30326853, 2018). "In preexisting blood vessels, stem-like ECs with a proangiogenic phenotype have been identified, and ECs that express ABCB1/P-gp have been reported in residential normal and tumor blood vessels." (PMID 29695087, 2018). "For example, VPA affected the expression of P-glycoprotein (ABCB1) in tumor cell lines and in rat livers and that of folate receptor α (FRα; FOLR1) in pregnant mice and in a human placental cell line." (PMID 30298005, 2018). "P-glycoprotein (ABCB1/MDR1) is one of the most studied ABC transporters that are overexpressed in many tumor types." (PMID 30515268, 2018). "In the tumour tissue sample, Western blot showed that ABCB1 protein was decreased in FTH1P3 knockdown group compared to empty vector group." (PMID 29971911, 2018). "ABCB1 promoter methylation was reported to suppress ABCB1 mRNA and protein expression in tumor cells." (PMID 28335443, 2017). "Epithelial or lamina propria mononuclear expression of ABCB1 protein was barely detectable across tumor-free and tumor tissues from CAC patients." (PMID 28686677, 2017). "In vivo, in tumor-bearing mice, nilotinib, acting as ABCB1 inhibitor, was found to increase the accumulation of DOX and DOXol in cancer tissues." (PMID 28283780, 2017). "Lamina propria mononuclear cells also stained positively for ABCB1 in tumor specimens from CRC patients, while scattered lamina propria mononuclear cells showed weak ABCB1 protein expression in healthy margins of CRC specimens." (PMID 28686677, 2017). "We confirmed previous observations that ABCB1 mRNA levels are lower in CRC tumor tissues when compared to morphologically normal tumor margin tissues." (PMID 28686677, 2017). "In contrast to the ABCC1 promoter which was found to be hypomethylated (methylation status < LOQ) in all tumor, tumor-adjacent and tumor-distant tissues, the ABCB1 and ABCG2 promoters were found to be methylated very frequently." (PMID 27689338, 2016). "Overexpression of ABCB1, ABCC1 and/or ABCG2 in tumor tissues is considered a major cause of limited efficacy of anticancer drugs." (PMID 27689338, 2016). "For each of the seven CpGs in the ABCB1 promoter, a statistically significant difference was found between tumor and tumor-adjacent tissues, tumor and tumor-distant tissues as well as between tumor and normal breast tissues of the control group." (PMID 27689338, 2016). "The seven CpGs in the ABCB1 promoter were found to be methylated (methylation status ≥ 5%) in at least eleven of the 16 tumor tissues." (PMID 27689338, 2016). "ABCB1/ P-glycoprotein (P-gp) /MDR1 are known to be expressed in the majority of drug resistant tumours." (PMID 27825361, 2016). "Overexpression of ABCB1, ABCC1 and ABCG2 in tumor tissues is considered a major cause of limited efficacy of anticancer drugs." (PMID 27689338, 2016). "Statistically significant differences were found in the ABCB1 promoter methylation status between tumor and tumor-adjacent tissue, tumor and tumor-distant tissue as well as between tumor and normal breast tissues from the control group." (PMID 27689338, 2016). "The investigational third-generation P-glycoprotein (ABCB1) inhibitor tariquidar has been used in clinical trials in tumour patients to overcome multidrug resistance." (PMID 27090254, 2016). "In the present study, we investigated the potential of TNP as a multifunctional nanocarrier for chemotherapy in an ABCB1 overexpressing tumor xenograft mouse model." (PMID 26716507, 2016). "In summary, simvastatin has a profound anti-tumor activity per se, which is now further highlighted by the fact that ABCB1 is downregulated in vitro and in vivo." (PMID 26319048, 2016).
tumor (continued). "Using the energy of ATP hydrolysis, ABCB1 pumps out a wide spectrum of chemotherapeutic drugs from tumor cells, including the taxanes, epipodophyllotoxins, vinca alkaloids and anthracyclines." (PMID 26824187, 2016). "Currently, the acquired high expression of P-glycoprotein (P-gp), the product of the human multidrug resistance gene (MDR1 /ABCB1), is the primary mechanism of tumor MDR." (PMID 26934120, 2016). "In general, plasma lapatinib concentrations greater than 2 μM were associated with tumor concentrations greater than 4 μM, which is the IC50 for inhibition of the efflux transporter ABCB1, that lapatinib has been shown to inhibit." (PMID 26571496, 2015). "The “downstream” promoter is normally used, but the minor “upstream” promoter is used in tissues expressing vast amounts of ABCB1 mRNA (such as the adrenal grand, liver and colon) or tumor cells overexpressing the ABCB1 gene." (PMID 29061940, 2015). "We next examined bosutinib anti-tumor activity as a function of ABCB1 overexpression in an in vivo xenograft model." (PMID 26149173, 2015). "The JNK pathway is also known to be involved in the downregulation of ABCB1 gene expression in several human tumor cells." (PMID 29061940, 2015). "In the drug-resistant tumor cell lines that were established from stepwise exposure to several drugs, ABCB1 transcripts from only upstream or both upstream and downstream were observed, along with increases in the amounts of the transcripts." (PMID 29061940, 2015). "In some previous studies in human medicine, it was shown that amplification of the ABCB1 gene was induced in several tumor cells by stepwise exposure to some chemotherapeutic agents, which is the conventional method to establish drug-resistant cell lines." (PMID 29061940, 2015). "These include the multidrug resistant efflux pump, MDR1/ABCB1, and the multidrug resistant-associated protein, MRP1, which are known to increase efflux of chemotherapeutic agents thereby allowing tumor (and normal) cells to evade drug-induced cytotoxicity." (PMID 26177450, 2015). "To investigate the significance of ABCB-1/P-gp down-regulation in vivo, we assessed ABCB-1/P-gp expression in tumor tissues." (PMID 25372840, 2014). "Enhanced Wnt5A was detected in the tumour biopsies, and significantly elevated Wnt5A and/or ABCB1 expression was shown in biopsied samples after chemotherapy." (PMID 25401518, 2014). "It is also reasonable to deduce that 3-BrPA can efficiently reverse the MDR of ABCB-1/P-gp overexpressing tumor cells, which with a high demand for ATP produced by glycolysis." (PMID 25372840, 2014). "Among the relapsed patients, 19 of the 24 (79%, P<0.001) of the biopsied samples showed significant increases of Wnt5A expression, and 21/24 (88%, P<0.001) of the tumor biopsies also showed a significant upregulated ABCB1 expression after chemotherapy." (PMID 25401518, 2014). "The percentage of ABCB1 expressing cells ranged from ~1% in the MED6 to 11.2% in the MED1 tumour of origin." (PMID 24887326, 2014). "Many compounds show the power to reverse resistance in tumor cells by down the expression of ABCB-1/P-gp." (PMID 25372840, 2014). "Firstly, we have demonstrated that > 40% of MB tumours express the ABCB1 multi-drug transporter, which is able to export many of the currently used chemotherapeutic drugs." (PMID 24887326, 2014). "Because it is known now that there are AP-1 binding sites on the promoters of ABCB1 blockage of tumor promoter-induced AP-1 activation inhibits neoplastic transformation." (PMID 23533531, 2013). "In vivo, we were able to significantly correlate the efficacy in CRC models to tumor uptake of PF-309 and found a significant correlation between ABCB1 expression and response in CRC cell line xenograft models." (PMID 23524533, 2013). "Conversely, there were four cell line xenograft models with <40% average tumor growth inhibition, all of which had high ABCB1 gene expression levels." (PMID 23524533, 2013).
tumor (continued). "We evaluated the tumor concentration in two tumor xenograft lines with high ABCB1 gene expression (SW480 and HCT15) and two tumor xenografts with low ABCB1 gene expression (GEO and HCT116)." (PMID 23524533, 2013). "From the cell line xenografts, we found a significant correlation between ABCB1 gene expression profiles and tumor response." (PMID 23524533, 2013). "Immunohistochemical analysis confirmed ABCB1 expression in PDAC tumor cells, mainly located at the apical surface of the cells (n = 11 PDAC samples)." (PMID 24069258, 2013). "In tumors with expected high tumor P-gp a ∼four fold lower concentration was observed than the tumors with low ABCB1 expression." (PMID 23524533, 2013). "Recently, VEGF was found to increase resistance to paclitaxel in tumour endothelial cells by inducing ABCB1 expression." (PMID 23143659, 2013). "We evaluated the tumor growth inhibition data and ABCB1 and ABCG2 gene expression data and found a significant correlation with ABCB1 (p = 0.02), but not with ABCG2 (p = 0.7), reinforcing what was observed in vitro." (PMID 23524533, 2013). "Within the 32-gene signature, genes upregulated in the pSP include previously proposed pancreatic CSC markers (CXCR4, CD133) or play a role in multidrug resistance (ABCB1) and in pathways important in tumorigenesis and tumor progression." (PMID 24069258, 2013). "As an example, clonal analysis of resistant cells strongly implicate MEIS1 as a modifier of ABCB1-mediated resistance, and this is further supported by our analysis of a large panel of tumor cells." (PMID 23442791, 2013). "The expression of ABCB1 was compared in the human cerebral microvascular endothelial cell line/D3 (hCMEC/D3) and the epithelial tumour line Caco-2, by FACS." (PMID 23133566, 2012). "The drug efflux activity of P-glycoprotein (P-gp, a product of the mdr1 gene, ABCB1 member of ABC transporter family) represents a mechanism by which tumor cells escape death induced by chemotherapeutics." (PMID 22312258, 2012). "Further studies will also be required to reveal the potential importance of an activated Wnt/β-catenin pathway for intrinsic ABCB1-mediated resistance in other tumour types." (PMID 22460269, 2012). "ABCB1 expression is inherently overexpressed in tumours of the colon, making them primarily chemotherapy-resistant towards a wide panel of anticancer drugs." (PMID 22460269, 2012). "The most common mechanism developed by tumor cells to escape a drug-induced death is displayed in intrinsic or acquired MDR phenotype by the overexpression of the drug-efflux protein ABCB1." (PMID 23259070, 2012). "High ABCB1 levels have been detected in normal tissues with excretory or secretory function, which include colorectal epithelium, and in tumours originating from these organs." (PMID 22460269, 2012). "We demonstrate that tumours heterozygous for mut β-catenin showed nuclear β-catenin together with overexpression of ABCB1." (PMID 22460269, 2012). "The expression of ABCG2 and P-glycoprotein (ABCB1) is also important for efflux of the Hoechst 33342 dye, a phenotypic characteristic that defines the “side population” of human tumor cells and stem cells." (PMID 24212632, 2011). "Among membrane transporters, the overexpression most frequently involves P-glycoprotein (P-gp), encoded by the ABCB1 gene, and has been closely associated with unfavourable prognostic index in cases of several types of tumours." (PMID 20335952, 2010). "Three amplification products in the ABCB1 gene were found to be methylated in 70%, 64% and 81% of the tumours." (PMID 20338046, 2010). "Increases in the levels of histone acetylation and ABCB1 gene expression in PBMCs, as well as ABCB1 gene expression in tumor biopsy samples increased in all samples following romidepsin treatment." (PMID 27713371, 2010).
tumor (continued). "The eight genes displaying variable DNA methylation patterns in a significant number of tumours (ABCB1, BRCA1, CDKN2A, FOXC1, GSTP1, IGF2, PPP2R2B and PTEN) within the discovery cohort were tested for association with survival by a logrank test." (PMID 20338046, 2010). "When chemotherapy agents cause DNA damage in tumor cells, P-gp is over-expressed due to the activation of MDR1/ABCB1 (one of two isoforms of P-gp)." (PMID 19865518, 2009). "Several chemotherapeutic agents active in SCLC patients (as doxorubicin, etoposide, or vincristine) are P-gp substrates, raising the question of the impact of ABCB1 expression in these types of tumours." (PMID 17667922, 2007). "Epigenetic mechanisms (histone acetylation, DNA methylation) have been shown to play a pivotal role in ABCB1 gene expression in several tumour cell systems." (PMID 17667922, 2007). "Tumour drug-resistant ABCB1 gene expression is regulated at the chromatin level through epigenetic mechanisms." (PMID 17667922, 2007). "Considerable progress has been made towards the definition of the regulatory mechanisms that control the expression of ABCB1 gene in tumour cells." (PMID 17667922, 2007). "Importantly, KSQ‐4279 combination here was shown to significantly sensitize the resistant tumor specimens to doxorubicin treatment, and a more significant enhancement in the antitumor effect was observed in the specimens with higher ABCB1 expression." (PMID 41328326, 2025). "However, co-administration of manidipine and PTX significantly suppressed tumor growth, suggesting that manidipine effectively reverses ABCB1-mediated MDR in vivo." (PMID 41154347, 2025). "The function of the BBB and the corresponding density of the cell monolayer remains unchanged even during changes at the tumor site; therefore, small molecules, including drugs, can be secreted by efflux pumps such as P-glycoprotein (P-gp, ABCB1) or breast cancer resistance protein (BCRP, ABCG2)." (PMID 40574095, 2025). "This indicates that ABCB1 may serve as a prognostic marker in anthracycline-based chemotherapy regimens in these tumor types and a target for the development of novel anthracycline derivatives." (PMID 40723843, 2025). "Notably, ABCB1 plays a crucial role in tumor drug resistance, where ROS can suppress P-glycoprotein function or alter its expression, indirectly affecting the cytotoxicity of chemotherapeutics." (PMID 40625749, 2025). "The observed structural features of cellular deterioration suggest that ABCB1 overexpression contributed to CDDP resistance in tumor cells, whereas melatonin induced mitochondrial remodeling that may have contributed to overcoming this resistance." (PMID 41189280, 2025). "ABCB1 expression significantly decreased with advancing tumor stage, with higher median expression observed in early-stage (Stage I/II) compared to late-stage tumors (Stage III/IV), consistent with earlier reports of its downregulation in colorectal carcinogenesis." (PMID 40791849, 2025). "Other factors contributing to TNBC drug resistance include overexpression of ATP-binding cassette (ABC) transporters such as P-glycoprotein (P-gp/ABCB1), which can actively pump chemotherapeutic agents away from the cancerous or tumour cell, limiting drug accumulation in the cell." (PMID 41002447, 2025). "This raises questions about the influence of tumor biology and resistance markers such as ABCB1 on treatment responses, suggesting that these variables may require further exploration in a larger patient cohort." (PMID 40699680, 2025). "Notably, the hypoxic environment at high altitudes shares similarities with tumor drug resistance: both can alter the expression and function of drug transporters, including ABCB1, thereby influencing drug metabolism and ultimately therapeutic efficacy." (PMID 40265153, 2025).